ETAA1 (ETAA1 activator of ATR kinase)
Description:
Replication stress response protein that accumulates at DNA damage sites and promotes replication fork progression and integrity. Recruited to stalled replication forks via interaction with the RPA complex and directly stimulates ATR kinase activity independently of TOPBP1. Probably only regulates a subset of ATR targets.
Synonyms: ETAA16
Tractability: Antibody: its Gene Ontology location is reachable by antibodies, with high confidence. PROTAC: UniProt records ubiquitination sites on it; ubiquitination databases record sites on it.
Gene: Protein-coding gene on chromosome 2 (67,397,322 to 67,412,089, forward strand). Ensembl gene ENSG00000143971.
Subcellular location: Nucleus
Subcellular location (Human Protein Atlas): Nucleoplasm; Cytosol; Nuclear speckles; Plasma membrane; Vesicles
Gene Ontology:
Molecular function: protein binding; protein serine/threonine kinase activator activity
Biological process: DNA damage response; mitotic G2/M transition checkpoint; positive regulation of protein serine/threonine kinase activity; regulation of DNA damage checkpoint; replication fork processing
Cellular component: nuclear replication fork; nuclear speck; nucleoplasm; nucleus
Genetic constraint (gnomAD): Loss-of-function variants: 45 observed, 67.98 expected, observed/expected ratio (o/e) 0.66, 90% interval 0.52 to 0.85. The upper end of that interval is the gene's LOEUF score, 0.85, which puts it in group 3 of 6, group 1 being the genes least tolerant of losing a copy. Missense variants: 1,061 observed, 1,063.6 expected, observed/expected ratio (o/e) 1, 90% interval 0.95 to 1.05. Synonymous variants: 361 observed, 370.13 expected, observed/expected ratio (o/e) 0.98, 90% interval 0.89 to 1.06.
Homologues: Orthologues: chimpanzee ETAA1 (94% identical), macaque ETAA1 (91% identical), dog ETAA1 (70% identical), pig ETAA1 (70% identical), rabbit ETAA1 (67% identical), guinea pig ETAA1 (61% identical), rat Etaa1-ps1 (53% identical), mouse Etaa1 (51% identical), tropical clawed frog etaa1 (24% identical), zebrafish etaa1b (15% identical), zebrafish etaa1a (14% identical).
Diseases named in the same sentence as ETAA1 in open-access papers:
ETAA1 is named in the same sentence as 19 diseases in open-access papers, as found by Europe PMC text mining. Sharing a sentence is not in itself a finding about the gene and the disease. The quoted sentences say what the papers report.
Abdominal obesity (1 paper, 2021). Excessive fat around the stomach and abdomen. "Seven out of eight identified WC-associated CpGs were also associated with BMI at PFDR < 0.05, and two CpGs cg15103625 in RSRC1 and cg07421368 in ETAA1 were found novel in both WC and BMI associations, indicating common methylation sites influenced by both general and abdominal obesity." (PMID 34670603, 2021).
bone tumor (1 paper, 2013). "Another gene, Etaa1, is homologous to ETAA1 (Ewing tumor-associated antigen 1; synonym: ETAA16) in humans, which is expressed on bone tumor cells of mesenchymal origin or sarcomas." (PMID 23179633, 2013).
colorectal cancer (1 paper, 2025). A primary or metastatic malignant neoplasm that affects the colon or rectum. "To date, ETAA1 has been reported to cause predisposition to pancreatic cancer and nonpolyposis colorectal cancer." (PMID 40995433, 2025).
Hodgkins lymphoma (1 paper, 2025). A heterogeneous group of malignant lymphoid neoplasms of B-cell origin characterized histologically by the presence of Hodgkin and Reed-Sternberg (HRS) cells in the vast majority of cases. "In case #4 (B-ALL), along with his father and paternal uncle who had Hodgkin’s lymphoma, we detected variants of both ETAA1 and DNHD1 genes." (PMID 40995433, 2025).
liver cancer (1 paper, 2024). An epithelial or non-epithelial malignant neoplasm that arises from the liver. "UALCAN analysis indicated a preferential up-regulation of ETAA1 and RPA1 in advanced liver cancer stages and in poorly differentiated tumor grades, when compared to normal tissue controls." (PMID 39660144, 2024). "Furthermore, we explored the clinicopathologic characteristics of RPA1-dependent, ETAA1-mediated events in liver cancer patients by analyzing the correlations between ETAA1 and RPA1 expression levels and liver cancer stages and tumor grades." (PMID 39660144, 2024).
lymphoma (1 paper, 2025). A malignant (clonal) proliferation of B- lymphocytes or T- lymphocytes which involves the lymph nodes, bone marrow and/or extranodal sites. "However, the COSMIC database includes variants of ETAA1 in lymphoma cell lines." (PMID 40995433, 2025).
cancer (5 papers, 2019 to 2025). A tumor composed of atypical neoplastic, often pleomorphic cells that invade other tissues. "Although still in the preliminary stages, these insights offer a promising framework for future studies exploring the molecular mechanisms of RPA1-dependent ETAA1 in cancer interventions." (PMID 39660144, 2024). "Among the DENR-regulated transcripts were several relevant to cancer, such as Klhdc8a, Etaa1, Map2k5, Slc20a1 or Vegfd." (PMID 30982898, 2019). "Notably, APE1 forms biomolecular condensates in vitro and in nucleoli independent of its nuclease activity to promote the ATR-Chk1 DDR pathway activation in cancer cells, and APE1 is proposed as a new direct activator of the ATR kinase, in addition to TopBP1 and ETAA1." (PMID 37216274, 2023).
tumor (3 papers, 2014 to 2024). "Importantly, significant associations between RPA1, ETAA1 and PD-L1 were identified (p<0.001), with these connections being specific to the tumor context." (PMID 39660144, 2024). "While admittedly our number of matched BBB and tumors is limited, the data from these specimens suggests that, later in oncogenesis, mutations in ATR pathway members, i.e., ATR and ETAA1, are being selected for as they observed in both the benign biopsy and its matched tumor." (PMID 32566745, 2020). "The third inter-genic signal, rs4141819 on 2p14 (borderline significant with P = 9.2 × 10−8 in Stage III/IV-enriched analysis) is located 227 kb away from ETAA1 (Ewing's tumor-associated antigen 1) that encodes a tumour-specific cell surface antigen in Ewing family of tumours (EFTs)." (PMID 24676469, 2014). "As immune signatures within the TME are predictive of tumor invasiveness and metastasis, we evaluated the impact of ETAA1 on the enrichment of various immune cell populations." (PMID 39660144, 2024). "Considering the potential interplay between PD-L1 translocation and tumor invasiveness, we next investigated the role of ETAA1 in this context, revealing a diverse landscape of tumor infiltrating lymphocytes (TILs) within the tumor microenvironment (TME) engaged by ETAA1." (PMID 39660144, 2024).
hematologic cancers (1 paper, 2025). "The ETAA1 gene may be a novel predisposition gene that emerges in hematologic cancers in both children and adults." (PMID 40995433, 2025).
ETAA1 also shares sentences with these, for which no sentence is quoted: breast carcinoma (1 paper); endometriosis (1); Fanconi anemia (1); glioma (1); hepatocellular carcinoma (1); migraine (1); neuropathy (1); Obesity (1); pancreatic cancer (1); sarcoma (1).